MYC (MYC proto-oncogene, bHLH transcription factor)
Diseases named in the same sentence as MYC in open-access papers (continued):
Sharing a sentence is not in itself a finding about the gene and the disease.
cancer (continued). "Additionally, the oncogene MYC, which is located in 8q24 and is known to be a driver in human cancers, revealed no significant changes after the silencing of FAM83H‐AS1." (PMID 33634993, 2021). "The ligands showed a clear binding preference for c‐MYC G4 [4e: ΔTm=23.4 °C (ligand concentration 1 μM, ligand:G4=5 : 1), Kd=1.08 μM; Cz1: ΔTm=15.8 °C (ligand concentration 1 μM, ligand:G4=5 : 1), Kd=0.21 μM] and acted as endogenous transcriptional regulators of c‐MYC gene in cancer cells." (PMID 34138492, 2021). "Searching the Cancer Cell Line Encyclopedia (CCLE) we found significantly lower levels of expression of several histone demethylases (KDMs), including KDM6A and KDM6B, in SMARCA4def compared with MYCamp cells or with LC cells that are wild type for SMARCA4 and MYC." (PMID 34262032, 2021). "Therefore, instead of directly targeting neoplastic MYC, our study theoretically justifies clinically approved PARP and ATM inhibitors that can be co-used to re-establish platinum sensitivity even in platinum-refractory cancer cells." (PMID 34948122, 2021). "The MYC protein, is generally present at very low levels in normal or quiescent cells but is rapidly induced following mitogenic signals transduced via multiple cellular pathways including MAPK, WNT, NOTCH, and PI3K that are also frequently deregulated in cancer." (PMID 33799592, 2021). "In fact, in many cancers, high expression of the RNA-binding protein LIN28 is responsible for a global post-transcriptional downregulation of let-7, leading to an increase in different oncogenic targets (MYC, RAS, HMGA2, and others) and promoting tumorigenesis and cancer progression." (PMID 34439740, 2021). "The KSHV protein vIL-6, while not directly responsible for upregulating MYC transcription or MYC protein expression, could enhance the oncogenic activities of MYC in a KSHV-associated cancer mouse model." (PMID 34066504, 2021). "Therefore, our findings reveal that SQLE is critical for MYC-mediated cholesterol synthesis, and further demonstrate that SQLE may be a potential therapeutic target in MYC-amplified cancers." (PMID 33791309, 2021). "However, the overlap between the MYC and cellular functions of CDK12 indicate that CDK12 could be an effective therapeutic target for MYC-dependent cancers." (PMID 33805800, 2021). "Interestingly, UBR5 suppresses MYC-dependent priming to therapy-induced apoptosis in cancer cells as it resets MYC to levels that are not enough to induce apoptosis, whereas in normal cells accumulated MYC triggers apoptosis." (PMID 34178666, 2021). "MYC proteins regulate a range of cellular processes and their dysregulation has a large impact on the development of cancer: different types of MYC and MYCN alterations have been identified in a large variety of cancers and they are often correlated with poor prognosis and reduced survival." (PMID 34689785, 2021). "In addition, investigating the specific role of SENPs, which, in normal cells, tightly control the SUMOylation equilibrium, could provide information for additional pharmacological intervention in MYC/SUMO-activated PDAC and other cancers." (PMID 33071285, 2021). "However, the key upstream regulators of TFs (e.g., MYC and E2F) involved in the regulation of AATs in cancer cells have not been reported yet." (PMID 34003553, 2021). "The transcription factor MYC, one of the most frequently amplified genes in human malignancies, is a master-regulator of amino acid metabolism promoting the expression of transporter proteins such as SLC1A5, SLC7A5 and SLC43A1 and thus, driving cancer growth by effective amino acid delivery." (PMID 33401748, 2021).
cancer (continued). "The main intracellular effect was an enhanced β-catenin transcriptional activity that positively influences c-MYC messenger expression, which is often deregulated in human cancers, and notably involved in cell cycle progression, thus confirming VDR involvement in cancer growth control." (PMID 32560347, 2020). "Interestingly, this direct regulation of MYC by IRE1α‐XBP1s is not restricted to cancer cells, as a recent study reports that XBP1s also upregulates MYC expression to promote proliferation of natural killer cells." (PMID 32310340, 2020). "For example, the MYC locus in SW480 cells contains 135 rearrangements in a 4-Mb genomic window, whereas a larger complex event was observed in HCC1954 cells around the similar locus, which also involved two other cancer driver genes, TERT and APC, on chromosome 5." (PMID 32024999, 2020). "Similarly, since we observed the decrease of mRNA export and of protein expression of c-MYC and cyclin D1 by disruption of the API5−FGF2 complex formation, the API5−FGF2 interaction can be an additional potential therapeutic target for cancers." (PMID 32383752, 2020). "It was shown that c-MYC could not only inhibit POX/PRODH expression primarily through increasing miR-23b* but also evidently increase the biosynthesis of proline from glutamine, maintaining cancer cell survival and proliferation." (PMID 33117704, 2020). "Indeed, a recent study shows that inhibition of the PVT1 transcription does not impact on MYC expression in a cancer cell line." (PMID 32369019, 2020). "Moreover, with functional experiments, we demonstrated that after inhibition of the miR-31-3p expression in HCT116 cancer cell line, the c-MYC expression considerably decreased, probably through a direct action of this miRNA on E2F2, a negative regulator of the c-MYC expression." (PMID 32164324, 2020). "Since both factors, SWI/SNF and MYC play an important role in the tissue-specific gene expression and cell proliferation, understanding and exploring the functional interconnection between MYC and SWI/SNF is critical in tracking the aggressiveness of MYC dependent cancers." (PMID 31932624, 2020). "Because the introduction of SOX2, OCT4, MYC, and KLF4 is sufficient to reprogram differentiated cells into iPSC with ESC properties, the combined expression of these factors has been hypothesized to initiate tumors and promote cancer progression." (PMID 32427884, 2020). "Interestingly, more and more studies show that inhibition of c-MYC is not always the main mechanism of JQ1 in cancer cells." (PMID 32157097, 2020). "c-MYC can increase the transcription of the β-catenin and VEGF genes, and, at the same time, β-catenin/TCF-Lef activity depends on c-MYC transcription in colorectal cells, suggesting that all these proteins collaborate in signalling loops to favour the development and progression of cancer cells." (PMID 33081077, 2020). "This may help explain why MYC and RAD21 are frequently co-amplified in many cancers." (PMID 32859084, 2020). "Other studies show that MYC activates angiogenesis by increasing the expression of Interleukin 1β and VEGF and suppressing Thrombospondin-1 (TSP-1), thereby facilitating the delivery of nutrients to cancer cells and allowing for the escape of cancer cells into the bloodstream." (PMID 33081056, 2020). "This higher efficacy might be explained by the E-antibiotics impacting both crucial short-lived proteins such as c-MYC and MCL-1 involved in stimulating cancer proliferation and survival, as well as mitoribosomes whose mt-r-proteins are translated by 80S ribosomes." (PMID 32151059, 2020). "g., transfection) of stemness genes, such as OCT3, SOX2, KLF4, MYC, NOTCH1, NANOG, and LIN28, as well as epithelial-mesenchymal transition (EMT) genes (ZEB1, SNAI, VIM, TWIST, etc.), leads to stem phenotype induction and increased stem-like cancer cell activity." (PMID 32523653, 2020).
cancer (continued). "However, in contrast to other cancers, we did not observe MYC-mediated transcriptional activation of DDR genes such as CHK1, PARP1, PARP2, and BRCA144–46." (PMID 31266951, 2019). "So, it seems not beneficial for cancer cells that MYC represses miR‐200b‐3p." (PMID 30451365, 2019). "In this context, URI1 induced by c-MYC may function as a negative-feedback regulator that allows cancer cells to adapt to metabolic stress and survive under glucose deprivation." (PMID 31739577, 2019). "Interestingly, c-MYC levels were unaffected upon glutamine withdrawal in these cancer stem cells, indicating no feedback loop in c-MYC regulation of glutamine metabolism." (PMID 31261718, 2019). "Cancer cells with c-MYC overexpression were more sensitive to QN-1, relative to normal cells." (PMID 31584090, 2019). "Western blotting, qRT-PCR, and luciferase reporter assays using cancer cell lines (HeLa and A549) revealed that TH3 is able to repress the transcription of c-MYC at a protein level without affecting BCL2 expression, suggesting the preferential recognition and stabilization of the c-MYC G4 by TH3." (PMID 30682877, 2019). "Although this does not seem beneficial for cancer cells, it might be that with the overall broad effects of MYC, lncRNA‐MIF is an additional factor in fine‐tuning the most optimal MYC levels." (PMID 30451365, 2019). "MYC, for example, is a well-known major driver of oncogenesis and has been identified as one of the most commonly deregulated oncogenes in a wide variety of cancer types, yet potent drugs directly targeting MYC are still not available." (PMID 29899872, 2018). "In addition to affecting the turnover of critical oncoproteins like MYC, USP28 may regulate other essential pathways in cancer progression." (PMID 29415985, 2018). "Furthermore, our demonstration of a novel synthetic interaction between MYC activation and CLK inhibition provides a better understanding of the functions of the MYC proto‐oncogene and CLK, and highlights the specific clinical application of the CLK inhibitor for MYC‐activated cancers." (PMID 29769258, 2018). "Other preclinical studies in cancer cell lines have also shown that other biological processes can also be concomitantly upregulated in the presence of higher uptake of FDG in tumors, as it happens in the activation of oncogenic pathways such as KRAS, PI3K, and c-MYC." (PMID 29349517, 2018). "Knowing that ID1 regulated self-renewal of both normal and cancer stem cells via Wnt/β-catenin dependent c-MYC transcription activation, and ID1 promoted c-MYC expression through MAPK/ERK signal pathway in HCC, we next explored whether ID1 enhanced c-MYC activities through these two pathways." (PMID 29169374, 2017). "Not surprisingly, inhibition of MYC has been suggested as an anti-cancer therapy." (PMID 29163823, 2017). "Thus, the MYC/MAX/MNT system that drives cell growth and proliferation is robustly set to an off state during normal homeostasis, whereas in cancer, the system is locked to a pathological on state." (PMID 28583252, 2017). "However, the roles of the HAT complexes during MYC function in cancer have not been well characterized." (PMID 29321817, 2017). "Prior to our study it was not clear whether the MYC dependence of cancer cells in vivo and normal cells in culture is due to shared regulatory mechanisms." (PMID 28583252, 2017). "The depletion of MYC by the co-transfection of antisense RNA of c-MYC in cell lines derived from human tumors shows inhibition of proliferation and induction of differentiation, serving as the first experimental evidence of MYC addiction in cancer cells in vitro." (PMID 28590415, 2017). "A deeper understanding about the cross-talk between the MYC proteins and PRC2 components represented in ESC-like signature, and how does an imbalance in this cross-talk lead to malignancy, would shed novel light on a reduced relapse and mortality rate of unfavorable cancers." (PMID 28984200, 2017).
cancer (continued). "However, as Eμ-MYC AtrS/S mice display drastically reduced lifespan and die of pleiotropic disease, this study failed to unambiguously separate the consequences of impaired ATR from impaired downstream CHK1 signaling for cancer formation." (PMID 29167438, 2017). "In respect to cancer, studies have shown that 1,25(OH)2D3 induces the expression of anti-proliferative and pro-apoptotic genes such as p21, p27, and BAX, and decreases the expression of oncogenic transcription factors like MYC and Hypoxia-Inducible factor 1-α (HIF1α)." (PMID 28124999, 2017). "Additionally, EGFR, HER2, c-MYC, and MET have been identified to be potential biomarkers that predict the efficacy of the pharmacological treatments targeted against protein products of these genes in various cancers." (PMID 28764718, 2017). "In HT1080 cells which have high basal level of MYC, overexpression of Menin increased cell glycolysis as measured by the extracellular acidification rate (ECAR) and glucose uptake and lactate production, indicating that Menin enhanced glycolytic metabolism in cancer cells." (PMID 28474697, 2017). "Thus, a negative cross talk between the MYC pathway and circadian oscillator is likely to exist in cancer cells." (PMID 28674522, 2017). "TIP60 inhibitors were efficacious in castrate-resistant prostate cancer and breast cancer in reducing proliferation and inducing apoptosis; however, to our knowledge TIP60 inhibition has not yet been applied as a therapeutic strategy for cancers that are specifically MYC-addicted." (PMID 28505071, 2017). "In some cancers, accumulation of high BCL-XL expressing cells might emerge from a negative selection induced by cell autonomous pro-apoptotic oncogenic signals such as these resulting from enhanced MYC or decreased pRB expression." (PMID 29066722, 2017). "However, despite extensive efforts in this regard, neither a specific pharmacologic inhibitor has been successfully translated into the clinical setting, nor the exact mechanism of how elevated MYC levels reprogram cells to promote cancer is known." (PMID 29100357, 2017). "Furthermore, the oncogenic dysregulation of the RAS, MYC and the MAPK pathways in cancer cells are known to induce the production of growth factors and cytokines such as VEGF, IL-6, IL-10, and IL-1β, leading to the recruitment and the tumorigenic transformation of macrophages." (PMID 28969664, 2017). "One of the common mechanisms of MYC deregulation in cancer is amplification, so it is amenable to detection by fluorescence in‐situ hybridization (FISH), and this can be a highly sensitive technique by which the MYC copy number can be studied at cellular resolution." (PMID 26826706, 2016). "It inhibited MYC expression however this was not related to its sensitivity in cancer cell lines." (PMID 27835869, 2016). "However, a comprehensive understanding of how PI3K/mTOR inhibitors target MYC proteins and a rationale for the selection of compounds likely to be clinically active against MYC-driven cancers is lacking." (PMID 27438153, 2016). "In addition, since MYC proteins are overexpressed in SCLC cells, higher dose of MYC inhibitor administration would be required than in cancer cells without MYC family genes amplification." (PMID 27105536, 2016).
cancer (continued). "It has been reported that SP1 could cooperate with MYC to activate transcription of the human telomerase reverse transcriptase gene (TERT), which is responsible for maintenance of the length of telomeres and its defects may lead to diseases including cancer." (PMID 26083494, 2015). "The absence of an effect of PNU on MYC mRNA, a well-known beta-catenin target gene, supports the hypothesis that MYC overexpression is common in many cancers but not in ACTs." (PMID 26515592, 2015). "In vHMEC, we observed enrichment of up- and down-regulated genes in the MYC and PRC modules, respectively (respectively, family-wise error rate P value <0.05) and no significant change in the CORE module genes (P = 0.06), similar to the expression pattern of cancer." (PMID 25960784, 2015). "Interestingly, comparison of multiple myeloma tumor cells and related healthy cells suggests that cancer cells “acquire” specific super-enhancers near oncogenes, since they tend to occur in a gene desert near c-MYC yet are absent in healthy cells." (PMID 26569311, 2015). "However, as many other strategies, targeting MYC is also a double-edged sword, and does not always promote cancer therapy under some circumstances." (PMID 26402672, 2015). "In addition to containing MYC and many MycSL hits from different screens, the CIBLIN list contains an astonishing number of known proto-oncogenes first discovered for their roles in cancer and/or cellular transformation." (PMID 26173873, 2015). "Furthermore, JQ1 sensitivity does not seem to correlate with MYC mRNA reduction, a common mechanism seen in other cancers." (PMID 26485762, 2015). "That is a strong possibility given that several oncogenes are regulated by FBXW7, including MYC, Notch, JUN and cyclin E. Thus, targeting different pathways in addition to the mTOR pathway might be necessary to effectively kill cancer cells in tumors driven by FBXW7 alterations." (PMID 24586741, 2014). "However, JQ1 does not inhibit MYC expression to a similar extent in all cancer cells, further underscoring that MYC transcription is perhaps under different controls in various cancer cell types." (PMID 24466310, 2014). "Based on the motif pair data, we hypothesized enrichment of binding by AP1/MYC pairs in our 4,102 promoters in the cancer models, relative to the non-cancer model." (PMID 24612742, 2014). "Overall, studies have shown that there is a multi-faceted interplay between mammalian sirtuin proteins and the MYC and HIF transcription factor families, potentially rendering some of the sirtuins attractive therapeutic targets to reverse metabolic reprogramming in cancer cells." (PMID 25085992, 2014). "It thus appears that many, if not all, routes to cancer converge on c-MYC." (PMID 24130880, 2013). "Interestingly, the inhibition of these enzymes results in cell death of the MYC-dependent cancer cells but not their differentiated counterparts." (PMID 24280108, 2013). "Although we have not directly proven the existence of a stable c-MYC (or other oncogene) i-motif under physiological conditions, it seems that at this time, continued research into targeting the i-motif, remains a viable and novel approach to cancer treatment." (PMID 24132198, 2013). "Therefore, MYC represents an attractive target for cancer therapy in humans, but currently no MYC inhibitor other than dexamethasone is clinically applicable." (PMID 23874405, 2013). "However, the metabolic differences between isogenic MYC-dependent cancer cells and their differentiated counterparts have not been studied." (PMID 24280108, 2013). "Therefore it is not surprising that direct or indirect deregulation of MYC expression occurs in the vast majority of human cancers." (PMID 23091802, 2012). "Interestingly, recent studies have demonstrated that besides its involvement in the control of cell proliferation, apoptosis, and differentiation, MYC contributes also in noncell-autonomous cancer process such as angiogenesis." (PMID 22383169, 2012).